MIR875 (microRNA 875)
Synonyms: hsa-mir-875; MIRN875
Gene: MicroRNA gene on chromosome 8 (99,536,786 to 99,536,861, reverse strand). Ensembl gene ENSG00000216069.
Gene Ontology:
Biological process: miRNA-mediated post-transcriptional gene silencing